CAV1 (caveolin 1)
Diseases named in the same sentence as CAV1 in open-access papers (continued):
Sharing a sentence is not in itself a finding about the gene and the disease.
liver fibrosis (23 papers, 2017 to 2025). "Over the years, the efficiency of mitochondrial respiration, loss of mitochondrial plasticity, and increase of Cav‐1 expression in HSC have been considered critical for the progression of liver fibrosis." (PMID 35971753, 2022). "Cav1 deficiency was found to aggravate CCl4-induced liver fibrosis in mice, which was mechanistically linked to enhanced TGF-β induced oxidative stress." (PMID 31718044, 2019). "iPSC-derived hepatocytes from normal and obese subjects are cultured to assess their lipid accumulation, via hepatic fibrosis pathways, by running transcriptome analyses to compare gene expression associated with hepatic fibrosis (caveolin 1 (CAV1) and cluster of differentiation 36 (CD36))." (PMID 40801620, 2025). "Similarly, a recent study also revealed that Cav1 deficiency aggravated CCl4 induced liver fibrosis in mice by regulation of oxidative stress." (PMID 29891777, 2018). "Hence, these implied that Cav-1-associated autophagy might occur in capillarized liver sinusoidal endothelium in liver fibrosis." (PMID 29760379, 2018). "Depletion of CAV1 attenuates hepatic fibrosis by promoting SQSTM1-mediated PFKL degradation in hepatic stellate cells." (PMID 40303344, 2025). "In liver fibrosis, for example, increased matrix stiffness leads to enhanced Cav1-mediated endocytosis and vesicular trafficking in hepatic stellate cells." (PMID 40149956, 2025). "CAV1 in turn internalizes TGF receptors into caveolae and this internalization represses the TGF-β signaling pathway, thereby establishing an important link between miR-199a-5p and CAV1 in liver fibrosis progression." (PMID 34575957, 2021). "BRG1 has also been demonstrated to activate the transcription of caveolin (CAV1), which in turn suppresses the production of NO and promotes liver fibrosis." (PMID 32733885, 2020). "We have previously shown that endothelial-specific deletion of BRG1 in mice attenuates bile duct ligation (BDL) and thioacetamide induced liver fibrosis by regulating the transcription of caveolin-1 (CAV1) and NADPH oxidase 4 (NOX4), respectively." (PMID 32478075, 2020). "In vivo, CAV1 scaffolding domain peptides were proven to dampen liver fibrosis by inhibiting TGF-β/Smad signaling." (PMID 32082178, 2019). "Further, a Cav1 scaffolding domain (CSD) peptide attenuated CCl4-induced liver fibrosis as shown by significantly decreased collagen content." (PMID 31718044, 2019). "To study the role of Cav1 in liver fibrosis, we measured the expression level of Cav1 after CCl4 injection in liver tissues of WT animals by semi-quantitative real-time PCR and Western blot." (PMID 29891777, 2018). "Collagen concentration was significantly reduced, whereas CAV1 expression increased after treatment of a bile duct ligation injury-induced liver fibrosis model with DEHR for four weeks." (PMID 30384491, 2018). "In this study, we found mRNA and protein levels of Cav1 were significantly reduced in the progress of liver fibrosis." (PMID 29891777, 2018). "Cav1 expression has been shown to be reduced and inversely correlated with high levels of miR-199a-5p, which is elevated in patients with liver fibrosis." (PMID 29891777, 2018). "A mouse model induced by carbon tetrachloride was used to identify the role of Cav1 in activation of hepatic stellate cells (HSCs) and collagen production in the progress of liver fibrosis." (PMID 29891777, 2018). "In liver fibrosis, our previous studies for the first time revealed that Cav-1-related autophagy, initiated by aldosterone-induced oxidation, promotes LSECs defenestration." (PMID 29760379, 2018). "This study indicates that Cav1 has a pivotal role in activation of HSCs and collagen production and suggests a potential therapeutic target for liver fibrosis." (PMID 29891777, 2018). "Thus, metabolic and flexibility shifts in mitochondrial plasticity by Cav‐1 associated with HSC activation report novel and potent targets for the treatment of liver fibrosis." (PMID 35971753, 2022).
liver fibrosis (continued). "This hypothesis was supported by a previous study where the authors showed that CAV1 can inhibit TGF-β/Smad signaling to relieve liver fibrosis in mice." (PMID 32082178, 2019). "DEHR ameliorates liver fibrosis in vitro and in vivo, possibly through a mechanism involving CAV1." (PMID 30384491, 2018). "In this study, we hypothesized that Cav1 deficiency would enhance TGF-β1/Smad signaling and CSD could inhibit the progression of liver fibrosis by restoring the inhibitory effect of Cav1." (PMID 29891777, 2018). "Autophagy initiated the degradation of Cav-1 during CCl4-induced LSECs defenestration and liver fibrogenesis; in contrast, autophagic inhibitor 3MA could inhibit autophagic degradation of Cav-1 to maintain fenestrae and attenuate liver fibrosis." (PMID 29760379, 2018). "Hence, these data suggested that serious autophagy initiated the degradation of Cav-1, along with F-actin remodeling and the downregulation of the NO-dependent pathway, during CCl4-induced LSECs defenestration in the early stage of liver fibrosis." (PMID 29760379, 2018). "Caveolin-1 (Cav1), the principal coat protein of caveolae, might act as a therapeutic target for treatment of liver fibrosis." (PMID 29891777, 2018). "In the WT mice, we measured decreased expression of Cav1 during the early stage of liver fibrosis." (PMID 29891777, 2018). "Although the precise roles played by DEHR in the suppression of fibrogenesis are yet unclear, our findings suggest that DEHR may be a candidate agent to resolve liver fibrosis likely through a mechanism that involves CAV1." (PMID 30384491, 2018). "Recent reports evaluating the pathogenesis of liver fibrosis have suggested that CAV1 may play an important role in chronic liver disease." (PMID 30384491, 2018). "Moreover, rats treated with dimethylnitrosamine (DMN) to induce liver cirrhosis demonstrate enhanced Cav-1-eNOS binding paired, with a positive correlation between Cav-1 protein expression and the degree of liver fibrosis." (PMID 28970796, 2017). "The role reversal of Cav-1 in liver fibrosis could be due to the fact that the cirrhotic liver contains higher levels of cholesterol, and Cav-1 is a major cholesterol binding protein, thus Cav-1 expression may be stimulated in chirrotic liver." (PMID 28970796, 2017). "However, the role of CAV1 is little known about in HSCs even in liver fibrosis." (PMID 28322315, 2017). "Previous research indicates that CAV1 can modulate iron death by influencing reactive nitrogen species (RNS) metabolism during acute immune-mediated hepatic damage and liver fibrosis." (PMID 40013149, 2025). "Among other genes, increased CD36 and CAV1 expression and decreased expression of CES1 in obese iPSCs could have been responsible for excess lipid accumulation, resulting in differential expression of genes associated with hepatic fibrosis, a key feature of non-alcoholic fatty liver disease (NAFLD)." (PMID 35915082, 2022). "In summary, SIRT1 drives the nucleophagic degradation of progerin mediated by the deacetylation of nuclear LC3 and improves the depletion of Lamin B1 and Cav-1, leading to the maintenance of LSEC fenestrae and the relief of liver fibrosis." (PMID 36497176, 2022). "We determined CAV1 expression and collagen concentration in the BDL-induced liver fibrosis model after treatment with DEHR." (PMID 30384491, 2018). "Besides, it was reported that Cav1 might negatively regulate human liver fibrosis." (PMID 29891777, 2018). "To identify Cav1 as an important negative regulator in the process of liver fibrosis, we delivered CSD to WT and Cav1−/− animals following CCl4 treatment and assessed whether CSD could inhibit the progress of fibrosis." (PMID 29891777, 2018). "We conclude that Cav1 is an important inhibitor of TGF-β1/Smad signaling in HSCs activation and collagen production, which might make it a promising target for therapy of liver fibrosis." (PMID 29891777, 2018).
liver fibrosis (continued). "Interestingly, during the first stage of CCl4-induced liver fibrosis, there was a time-dependent elevation of LC3 II/I protein expression, along with the decrease of Cav-1 protein level in LSECs." (PMID 29760379, 2018). "Although the interaction between Cav1 and multiple signaling molecules such as MAP kinase family and Smad has been studied extensively, it is still not clear whether these Cav1-mediated signaling pathways can be targeted as prospective therapies in liver fibrosis." (PMID 29891777, 2018).
ischemia (22 papers, 2012 to 2026). A hypoperfusion of the BLOOD through an organ or tissue caused by a PATHOLOGIC CONSTRICTION or obstruction of its BLOOD VESSELS, or an absence of BLOOD CIRCULATION. "It is likely that polymorphisms in the Cav-1 gene increase high plasma triglyceride levels, resulting in endothelial function abnormality and ischemia." (PMID 28346478, 2017). "It is further unknown if the regulation of AQP4 cell-surface expression by Cav1 can significantly affect the cellular swelling associated with ischemia, especially given that this process may be dominated by osmotic gradients between oxidatively-stressed astrocytes and the extracellular space." (PMID 29326556, 2017). "Specifically, Per2 and Cav1 have been shown to promote microglial polarization and inflammatory responses, which are essential for mitigating brain injury following ischemia." (PMID 40292254, 2025). "In conditions such as ischemia and lipopolysaccharide-induced injury, Cav-1 expression increases early, contributing to a decrease in claudin-5 and occludin, resulting in the breakdown of the BBB." (PMID 38922036, 2024). "Caveolin-1 (Cav-1), as a caveolae scaffolding protein, predominated in the transcytosis process instead of the paracellular barrier in the early stage of ischemia/reperfusion (IR)." (PMID 36855156, 2023). "The effect of ischemia on caveolin-1 levels and co-immunoprecipitation of caveolin-1 with N- or C-terminal fragments of the APP (N-APP and C-APP) and ADAM10 was also investigated." (PMID 36289917, 2022). "In endothelium-specific Cav-1-KO mice, angiogenesis in both the isolated aortic ring assay and hindlimb ischemia animal model was impaired." (PMID 35557625, 2022). "Cerebral infarct volume was significantly upregulated in CAV-1 KO mice compared with WT mice following focal cerebral ischaemia/reperfusion (I/R) injury in the mouse brain." (PMID 36253854, 2022). "In our previous study, Cav-1−/− mice showed significantly greater degradation of tight junction (TJ) proteins and proteolytic activity of matrix metalloproteinase (MMP) compared with Cav-1+/+ mice following photothrombotic ischemia." (PMID 27708218, 2016). "Immunoblot densitometry revealed marked increases in the Cav-1 protein levels in the ischemic hemisphere of photothrombotic rats 6, 9, and 12 h and 1, 3, and 7 d after the ischemia (P < 0.01)." (PMID 27708218, 2016). "We propose that ischemia-induced NO initiates S-nitrosylation of Cav-1, and tPA-activated ERK signal pathway stimulates the expression of MMP2 and 9 and shedding of S-nitrosylated Cav-1." (PMID 26881424, 2016). "Taken together, the results of these studies suggest that endothelial Cav-1 is essential for optimal recovery after ischemia-induced injury in mouse models of ischemia." (PMID 26605130, 2012). "For example, we demonstrated that loss of Cav-1 expression disrupts NMDA receptor signaling and attenuates pro-survival Src and ERK1/2 phosphorylation in response to NMDA or simulated ischemia." (PMID 23060817, 2012). "As expected, chronic ischemia-induced myelin proteins reduction was rescued in the Cav-1 overexpression group, suggesting that endothelial Cav-1 may be an important intermediary in ischemic demyelination." (PMID 36357389, 2022). "Similarly, in systemic Cav-1-KO mice, disrupted endothelial network formation was found in a hindlimb ischemia model." (PMID 35557625, 2022). "In addition, a CAV1-knockout mouse study demonstrated the role of endogenous CAV1 in promoting neovascularization, astrogliosis, and scar formation after ischemia." (PMID 36118760, 2022). "On the other hand, CAV1 was unaltered in coronary arterioles after ischemia." (PMID 32082483, 2020). "Thus, the balance of caveolin-1 during ischemia may affect APP processing and the degree of damage to brain cells after ischemia." (PMID 36289917, 2022).
ischemia (continued). "Here, we report that Cav-1 is upregulated in distal tubule epithelial cells (TECs) in both AKI patients and mouse models induced by ischemia/reperfusion injury (IRI) and lipopolysaccharide (LPS)." (PMID 42102380, 2026). "Expression of Caveolin-1, VEGF, eNOS, neovascularization, and apigenin interventions at different time points after ischemia/reperfusion was measured." (PMID 30622670, 2018). "To the best of our knowledge, we report for the first time a beneficial effect of Cav-1 OE on brain edema and BBB disruption following the induction of ischemia with MCAO." (PMID 27708218, 2016). "Cav-1 expression and BBB disruption peaked 12 h after the photothrombotic ischemia, whereas the vasogenic brain edema peaked 3 d after the MCAO." (PMID 27708218, 2016). "Caveolae-mediated endothelial transcytosis (especially that mediated by caveolin-1) is enhanced within hours after ischemia, prior to and independent of tight junction disintegration (2 days later)." (PMID 41292262, 2025). "In rat cortical cold injury model and cerebral I/R model, Cav-1 upregulation occurred before TJs breakdown, and in early stage of ischemia, BBB leakage resulted mainly from Cav-1-dependent transcytosis, suggesting Cav-1 is a potential therapeutic target for BBB integrity." (PMID 36855156, 2023). "Though the serum Cav-1 levels of patients with acute ischemic stroke were tremendously higher than the control group and the MMD group, patients with recurrent episode of ischemia or infarction (the Matsushima scale I–V) were comparable with that in patients in the Matsushima scale VI." (PMID 35557625, 2022). "Here the authors show Cav-1 stabilizes interactions and mediates OPC maturation in ischemia." (PMID 36357389, 2022).
Sepsis (22 papers, 2011 to 2025). Sepsis is defined as life-threatening organ dysfunction caused by a dysregulated host response to infection. "A proteomic analysis study demonstrating that the loss of CAV-1 promotes EndMT in HUVEC cells treated with serum from patients with sepsis also suggests that CAV-1 inhibits the EndMT process." (PMID 39200259, 2024). "Cav–1–deficient mice were more susceptible to death by polymicrobial sepsis when compared to the wild–type mice, exhibiting distinct inflammatory responses." (PMID 35911737, 2022). "Another microorganism such as Trichomonas vaginalis related to infection in pregnancy and associated with preterm delivery and postabortion sepsis was internalized in a caveola–dependent way overexpression of Cav–1 played a regulatory role during the uptake of extracellular vesicles." (PMID 35911737, 2022). "Thus, studies are essential to clarify the mechanisms underlying cellular apoptosis regulated by Cav–1 and its contribution as a modulator of the inflammatory response during sepsis." (PMID 35911737, 2022). "LPS-mediated CD14 activates Src-Tyrosine kinase to phosphorylate caveolin-1 at Tyr in endothelial cells, Cav-1 specific.In sepsis-induced lung inflammation and injury, LPS triggers the association of Cav-1-pTyr14 with TLR4, thereby inducing NF-kappa B signaling for proinflammatory cytokines." (PMID 36559147, 2022). "Finally, the role of Cav-1 in altering cell permeability during inflammation, in sepsis caused by microorganisms, apoptosis/autophagy activation and new therapies under study are discussed in this mini-review." (PMID 35911737, 2022). "Through its regulation of ROS, Cav-1 influences immune cell function and modulates apoptosis and autophagy during sepsis." (PMID 40041164, 2025). "To address this question, we first established the susceptibility of Cav1-/- mice and wildtype littermates (Cav1+/+) to S. aureus strain LUG1799 (WT edinB) in a model of septicemia." (PMID 38517935, 2024). "Cav–1 positive cells exhibited reduced protein expression in the septic lung and apoptosis increased significantly after sepsis induction." (PMID 35911737, 2022). "In this mini-review we demonstrate developments on cellular pathogenesis and the role of Caveolin-1 (Cav-1) in sepsis." (PMID 35911737, 2022). "Due to the important role of caveolae in signal transduction and based on evidence on the protective role of Cav-1 in the inflammatory response, the present review will focus on the role of Cav-1 during sepsis." (PMID 35911737, 2022). "Then, regulatory role of Cav–1 in autophagy process should drive research to establish new therapeutic strategies for sepsis treatment." (PMID 35911737, 2022). "A novel mechanism of autophagy induced by synthetic iron oxide–based nanoparticles (SPIONs) in mononuclear cells through activation of the Cav1–Notch1/HES1 signal pathway promoted inhibition of inflammation in the sepsis and liver injury model." (PMID 35911737, 2022). "The use of KO mice has allowed a more significant analysis of Cav–1 in the regulation of cell signaling in different models of sepsis." (PMID 35911737, 2022). "Data also showed that Cav–1 KO mice showed increased apoptosis in the thymus and altered T lymphocyte homeostasis during sepsis." (PMID 35911737, 2022). "A study demonstrated that part of host defense during sepsis is directed towards the control of Cav–1 protein expression in the pulmonary endothelium and regulation of apoptosis through PAR–1/EPCR specificity." (PMID 35911737, 2022). "Evidence of Cav1 modulation on eNOS activity during the regulation of innate immunity and sepsis–induced lung injury has been reported." (PMID 35911737, 2022). "Studies have shown that Cav-1 has a significant role in sepsis through the regulation of membrane traffic and intracellular signaling pathways." (PMID 35911737, 2022). "typhimurium, suggesting that Cav–1 palys a role in immunity against bacterial pathogens and responds to bacterial infections differently during sepsis." (PMID 35911737, 2022).